CD47 (CD47 molecule)
Diseases named in the same sentence as CD47 in open-access papers (continued):
Sharing a sentence is not in itself a finding about the gene and the disease.
tumor (continued). "In addition to MC38, CT26 and A20 tumor models also demonstrated the essential role of tumor cell-intrinsic IFN-I signaling, but not IFN-II signaling, in the context of CD47-SIRPα blockade therapy." (PMID 38982116, 2024). "Also, ADCP of CEACAM5+/CD47+ tumor cells induced by NILK-2401 was not impacted by the presence of a CD47 sink (i.e., presence of CD47-positive RBCs)." (PMID 38720892, 2024). "Similar to CD47, ICAM1 is expressed on the tumor cells and not the macrophages." (PMID 38339779, 2024). "This suggests that, in some tumor types, IFT57 rather than the coregulated CD47 mRNA expression could be the dominant driver of survival." (PMID 39201643, 2024). "As expected, CD47 expression was significantly higher in NHL patients than in healthy controls, and in NHL samples, CD47 expression was also higher in CD19+ tumor cells than in non-tumor cells, which were further confirmed by western blotting analysis and qPCR assay." (PMID 37781520, 2023). "Our results verified peri-tumoral infiltration level of CD68+ macrophages compared to paired tumor samples of no BTS group and HL group, indicating macrophage-based therapeutics like CD47 blockade that promotes macrophage phagocytosis 40 being possibly feasible." (PMID 37215452, 2023). "Since the SIRPα/CD47 axis is a myeloid checkpoint, this could explain why IgA-stimulated neutrophils from NXG mice are not able to kill tumor cells properly." (PMID 37338671, 2023). "The CTCL-specific strategies in future therapies targeting the CD47-SIRPα axis may go in two directions: agents without an Fc fragment to engage only macrophages and therapies utilizing Fc fragments to boost ADCC and tumor killing by NK cells." (PMID 36429020, 2022). "Meanwhile, our results indicated that there was no obvious tumor cells in the anti-CD47 and anti-CD274 group, suggesting that synergy CD47 antibody and CD274 antibody could effectively prevent CTCs from forming metastases in the lungs." (PMID 30872703, 2019). "Interestingly, we found that tumours from CD24- cells did not express the CD24 protein, and neither did they express the stemness markers CD47, EpCAM and Oct3/4." (PMID 25932953, 2015). "Our work therefore highlights the need to assess whether patients’ tumor cells are functionally resistant to BCL-2 inhibition with techniques such as BH3 profiling, and if that is the case, to explore switching to CD47 blockade alone rather than combining with a BCL-2 inhibitor." (PMID 41484790, 2026). "However, combined PD-L1 and CD47 blockade did not significantly improve upon either NDV-αCD47 or NDV-sPD1 treatment alone, and similar increases in tumor volumes were observed, although one mouse in the combined CD47 and PD-L1 blockade group experienced complete remission (CR)." (PMID 41322194, 2025). "This includes blocking “do not eat me” signals like CD47-SIRPα or CD24-Siglec-10 to enhance phagocytosis by macrophages, inhibiting monocyte recruitment or differentiation via pathways like CSF-1/CSF-1R, or attempting to repolarize M2-like TAMs towards an anti-tumor M1-like state." (PMID 40458806, 2025). "We further analyzed CD47 IHC changes in patients who had matched tissue available from TURBT and RC samples; as a result, patients who underwent a complete pathologic response with no tumor identified on RC were not studied due to a lack of post-treatment tumor." (PMID 37373873, 2023). "Notably, chemotherapy without CD47 blocking strategy enhances CD47 expression on tumor cells via inducing IL-18 release from macrophages, which increases L-amino acid transporter 2 (LAT2) in tumor cells." (PMID 37380989, 2023). "Expression of PD-L1 (the immune-checkpoint inhibit protein), CD47 (key molecule expressing ‘do not eat me signal’) and apoptotic protein FAS (also named TNFRSF6, Tumour Necrosis Factor Receptor Superfamily Member 6) are all crucial in participating the immune-escape mechanism of tumour cells." (PMID 35685372, 2022).
tumor (continued). "As a result, anti-CD47 therapy for SGC might not be a ‘silver bullet’, as many TIICs would also be affected, especially in MEC tumors where CD47 is more expressed in TIICs than in tumor cells themselves." (PMID 36171566, 2022). "Indeed, the addition of a CD47-specific blocking mAb to gefitinib-treated or untreated HCC827 and H1975 cells significantly increased the percentage of DiO-positive dendritic cells, while addition of an isotype control did not affect tumor cell engulfment." (PMID 32082304, 2019). "Finally, analysis of tumor protein lysates on antibody microarrays demonstrated an increase in pro-inflammatory cytokines, such as CXCL10, and a decrease in angiogenic proteins in debulking + anti-CD47 vs non-debulking + IgG tumors." (PMID 28076333, 2017). "Studies show that TTI-621 could block the “do not eat me” signal of CD47 and boost phagocytosis and anti-tumor effect, and intra-tumoral injections of TTI-621 are used to treat patients with mycosis fungoides and/or Sézary syndrome, which result in a rapid decrease in tumor size." (PMID 37510993, 2023). "A series of bispecific antibodies combining anti-CD47 specificity with anti-PD-L1, -EGFR, -CD19, or -CD20 activity may preserve tumor-specific phagocytosis-stimulating activities while sparing the host cells that do not express the tumor antigen, thus limiting toxicity." (PMID 38033495, 2023). "Moreover, targeting CD47 in a mouse model of esophageal squamous cell cancer not only enhanced proinflammatory responses and increased infiltration of CD8+ T cells within the tumor, but also increased PD-1 and CTLA-4 expression, thus increasing mouse susceptibility to anti-PD-1 and CTLA-4." (PMID 35053602, 2022).
cancer (1,104 papers, 2008 to 2026). A tumor composed of atypical neoplastic, often pleomorphic cells that invade other tissues. "Cluster of differentiation 47 (CD47) has been reported to overexpress in various malignant tumors and is associated with inferior prognosis." (PMID 41811881, 2026). "CD47-mediated inhibition of macrophage phagocytosis leads to the loss of the first line of defense against cancer cells." (PMID 40296909, 2025). "CD47, an integrin-associated receptor, is widely expressed on the surface of many cell types, including red blood cells and cancer cells." (PMID 40013150, 2025). "An antibody‐toxin conjugate targeting CD47 linked to the bacterial toxin listeriolysin O for cancer immunotherapy." (PMID 40878391, 2025). "It is widely recognized that cancer cells can upregulate integrin-associated protein (CD47) expression to exploit this “don’t eat me” signal to evade macrophage-mediated clearance and achieve immune evasion." (PMID 40589735, 2025). "CD47, an integrin-associated protein, is known as an antiphagocytic molecule linked to a worse prognosis in cancer patients." (PMID 40214484, 2025). "This role has been extensively studied in the context of cancer, However, in recent years, increasing research has shown that CD47 is closely associated with metabolic diseases such as diabetes, coronary atherosclerosis, and MASLD." (PMID 40630093, 2025). "CD44 mediates homotypic targeting, whereas CD47 interacts with integrin-associated proteins to assist cancer cells in evading macrophage-mediated phagocytosis within the immune system." (PMID 40528159, 2025). "Elevated CD47 expression across various cancer types has been linked to enhanced immune evasion and unfavorable prognostic outcomes." (PMID 39857116, 2025). "CD47 overexpression is associated with increased migrationand invasion at the cancer cellular level and worse prognosis in theclinic." (PMID 38558434, 2024). "CD47 blockade on red blood cells prevents the therapeutic from reaching cancer cells and causes anaemia by inducing red blood cell phagocytosis and agglutination." (PMID 38831013, 2024). "Cancer cells exploit this mechanism by overexpressing CD47 on their surfaces, causing macrophages to recognize them as “normal” cells and thus evade macrophage-mediated phagocytosis." (PMID 39664519, 2024). "CD47 demonstrated ubiquitous expression across various cancer types and was notably associated with unfavorable prognostic outcomes in pan-cancer assessments." (PMID 38720108, 2024). "With CD47’s overexpression linked to poor cancer outcomes, its pathway has become a target in cancer immunotherapy." (PMID 38247566, 2024). "This study conducted a comprehensive analysis of the prognostic and immunological implications of CD47 in pan-cancer, with a specific focus on its association with CD8 + T cell exhaustion." (PMID 38720108, 2024). "In other cancers, previous studies have demonstrated the association between CD47 protein expression and poor clinicopathological characteristics, suggesting the contribution of CD47 in the evasion of cancer cells from immune surveillance." (PMID 39594611, 2024). "By blocking CD47, this protective signal can be disrupted, making cancer cells more susceptible to immune-mediated destruction." (PMID 39275127, 2024). "An association between high CD47 expression and poor cancer survival has been attributed to its function on malignant cells to inhibit phagocytic clearance." (PMID 39201643, 2024). "Clinically, CD47 overexpression has been associated with worse prognoses in some cancer types, further supporting the role of this pathway in tumorigenesis." (PMID 38319147, 2024). "In some cancers, CD47 expression is associated with advanced stage at diagnosis, lymphogenous metastases, and relapse." (PMID 39201801, 2024).
cancer (continued). "The antiphagocytic function of CD47 contributes to the association of poor survival with higher CD47 expression in some cancers, but we cannot exclude that coregulation of IFT57 also contributes to the survival deficits in tumors with high CD47 expression." (PMID 39201643, 2024). "The regulation of integrin-associated protein CD47 by radixin has been linked to poor prognosis of cancers." (PMID 39457653, 2024). "CALR is reported as a pro-phagocytic protein with CD47, a transmembrane integrin-associated protein as its ligand, which prevents cancer cell phagocytosis." (PMID 36943734, 2023). "The delivery anti-CD47 blocks the “don’t eat me” signal of cancer cells, causing macrophages to engulf more cancer cells." (PMID 36976060, 2023). "Enhancement of antigen presentation ability and CD8+ T-cell proliferation in vitro are primarily caused by increased cancer cell phagocytosis brought on by the interruption of CD47/SIRPα cross-talk." (PMID 38033495, 2023). "Higher expression of CD47 is observed in broad types of cancers associated with lower prognosis and an increase in mortality." (PMID 36774400, 2023). "Cancer cells were reported to evade clearance by immune cells through the overexpression of antiphagocytic surface proteins, including CD47 and programmed cell death ligand 1 (encoded by CD274)." (PMID 36596773, 2023). "The review also discusses current and potential CD47-targeted therapies being explored for cancer treatment and delves into the associated challenges and opportunities inherent in targeting CD47." (PMID 38188674, 2023). "We have shown that CALR interacts with CD47, an integrin-associated transmembrane protein, which stimulates the escape of cancer cells from immune surveillance." (PMID 36943734, 2023). "A direct association of CD47 expression by cancer cells and the % FOXP3+ TILs (p = 0.01, r = 0.25) was also noted." (PMID 35406573, 2022). "Several studies had reported that the CD47 overexpression is associated with poor prognosis and clinicopathological variables in different cancer patients." (PMID 35281519, 2022). "To further explore the correlation between CD47 expression and the extent of immune infiltration, we investigated the association between CD47 and the expression of 47 immune checkpoint genes among 33 cancer types." (PMID 35697717, 2022). "In conclusion, CD47 expression was associated with adverse clinicopathological parameters and cancer-specific survival in patients with ccRCC." (PMID 36291980, 2022). "High expression, however, of SIRPα by CD68+ TAMs was linked with CD47 expression by cancer cells, low TIL-score, and poor prognosis." (PMID 35406573, 2022). "Cancer cells can evade recognition by the immune system by up-regulating integrin-associated protein (CD47)." (PMID 35664731, 2022). "A direct association of CD47 expression by cancer cells and the % FOXP3+ TILs (p = 0.01, r = 0.25) and with the FIL-score (p = 0.004, r = 0.28) was noted in linear regression analysis." (PMID 35406573, 2022). "CD47, a member of the immunoglobulin family, is one molecule that is overexpressed in a variety of cancer cells and is associated with clinical features and poor prognosis in a variety of malignancies." (PMID 35433462, 2022). "In contrast, high SIRPα expression by CD68+ TAMs (SIRPα/CD68-ratio) was linked with CD47 expression by cancer cells, low TIL-score, and poor prognosis (p = 0.02)." (PMID 35406573, 2022). "CD47 expression is enriched for cancer stem cells, and the depletion of cancer stem cell is led by deficiency of CD47." (PMID 36014432, 2022). "In the survival analyses, positive CD47 expression was associated with cancer-specific survival (p = 0.003)." (PMID 36291980, 2022). "The increase in CD47 by exogenously supplied IL-1β and GM-CSF also sufficed to overcome the enhanced sensitivity of cancer cells to phagocytosis caused by knockdown of SIRPγ." (PMID 35229723, 2022).
cancer (continued). "The functions of anti-CD47 include the inhibition and causation of efficient “self” signal uptake of cancer cells." (PMID 35464451, 2022). "The attachment of signal regulatory protein alpha (SIRPα) on macrophages to CD47, a “don’t eat me” signal on cancer cells and colony-stimulating factors, secreted by cancer cells, polarize tumor-associated macrophages (TAMs) to a tumorigenic M2 phenotype." (PMID 36612158, 2022). "One report has suggested CD47 overexpression in the CD90high cells of PanNET (cancer stem cell) and is associated with decreased survival of PanNET cells." (PMID 33765961, 2021). "Expression of CD47 is broadly elevated in cancers, and in some cancers, higher CD47 expression is associated with poor survival." (PMID 33925464, 2021). "This would predict decreased localization of CD47 to the surface of cancer cells, making them more susceptible to apoptosis compared to normal alveolar cells." (PMID 34521731, 2021). "Although these strategies have shown high efficacy, the antigen sink caused by overexpressed CD47 on cancer cells reduces bioavailability and increases potential toxicity to normal cells." (PMID 35111663, 2021). "Elevated CD47 expression in some cancers is associated with decreased survival and limited clearance by phagocytes expressing the CD47 counterreceptor SIRPα." (PMID 33925464, 2021). "We used different expression marker genes in CTCs to identify a cluster of cells that highly expressed cancer-associated cell-surface markers and expressed low level of HLA-I class proteins and other proteins, such as CD47." (PMID 34953500, 2021). "The expression of CD47 also has an important impact on the construction of TME, whereas CD47 deficiency led to cancer stem cell depletion." (PMID 34717705, 2021). "Casey and co-authors found that the MYC gene regulates the expression of CD47, PD-L1, and genes associated with immune signaling pathways, which ultimately makes cancer patients resistant to PD1 treatment." (PMID 35008249, 2021). "The effect of NTP on CD47-expressing cancer cells was identified in vitro and in vivo, and the underlying mechanism of action was investigated in silico." (PMID 33540720, 2021). "In the preclinical pharmacokinetic study, c4D10 effectively inhibited the CD47‐SIRPα interaction, which caused an acute depletion of cancer cells, even with only a limited contribution of antibody‐dependent cellular phagocytosis." (PMID 33449453, 2021). "The sensitivity to death by cancer therapy seems paradoxical given the protective roles of TSP1 or CD47 deletion on tissue survival of injuries caused by ischemia or ionizing radiation." (PMID 33925464, 2021). "Given its common high expression in malignant cancer cells, CD47 is associated with a poor clinical prognosis and metastasis and is thus considered a potential therapeutic target." (PMID 31899582, 2020). "Since high CD47mRNA expression is associated with poor survival of cancer patients, antibodies anti-CD47 were studied in various preclinical models and are currently being tested in ongoing clinical trials." (PMID 33574894, 2020). "Accordingly, in a wide range of human cancers, CD47 expression levels are associated with a worse outcome, and multiple clinical trials have started to evaluate its neutralization by monoclonal antibodies, in particular by combinatory strategies." (PMID 32962159, 2020). "Some studies have shown how CD47 expression is upregulated in cancer cells, whereas the regulatory mechanism underlying Sirpα expression in TAMs is still not clear." (PMID 32296015, 2020). "Here, we derived a macrophage-resistant cancer model from cells deficient in the expression of CD47, a major “don’t eat me” signal, via a macrophage selection assay." (PMID 33603751, 2020). "Cancer cells hijack this inhibitory CD47–SIRPα pathway by overexpressing CD47, which is associated with poor prognosis in both solid and hematological cancers." (PMID 33105656, 2020).